MDM2 (MDM2 proto-oncogene)
Diseases named in the same sentence as MDM2 in open-access papers (continued):
Sharing a sentence is not in itself a finding about the gene and the disease.
lung carcinoma (continued). "Data on the contribution of MDM2 SNP309 to the developmentof lung cancer are very contradictory." (PMID 33959694, 2020). "On the other hand, the MDM2 rs2279744 polymorphism showed significant associations with the risk of lung cancer among nonsmokers (OR (95% CI) = 1.334 (1.125–1.581), P = 0.001)." (PMID 32513119, 2020). "MDM2 overexpression is the most common alteration especially in lung cancer patients." (PMID 31440117, 2019). "However, only MDM2 gene exists in the cellular genomes of human malignancies such as lung cancer and colon cancer." (PMID 31440117, 2019). "Moreover, for every unit increase in the relative expression of MDM2 gene, the odds of having early-stage lung cancer increased by 12.36 and 4.43 for advanced-stage disease." (PMID 27418131, 2016). "Together, these findings suggest that HDAC2 might be an important molecular player in the regulation of Mdm2 and survivin expression levels in lung cancer cells." (PMID 25605253, 2015). "They further suggest that HDAC2 may exert a dominant effect on lung cancer cell survival by sustaining Mdm2-survivin levels." (PMID 25605253, 2015). "Interestingly, lung cancer patients carrying NRF2 SNP homozygous alleles (c.–617A/A) and the 309T (WT) allele in the MDM2 gene exhibited remarkable survival over 1,700 days after surgical operation (log-rank p = 0.021)." (PMID 24040073, 2013). "Finally, we also show that hsa-miR29b plays an important role as a tumor suppressor in lung cancer by targeting murine double mutant 2 (MDM2), revealing novel nodes for Wnt7a/Fzd9-mediated regulation of NSCLC cell proliferation." (PMID 23862015, 2013). "Finally, we show for the first time that hsa-miR29b plays an important role as a tumor suppressor in lung cancer by targeting murine double mutant 2 (MDM2), revealing novel nodes for Wnt7a/Frizzled9-mediated regulation of NSCLC cell proliferation." (PMID 23862015, 2013). "Subgroup analysis of gender, histology and smoking status suggested that the MDM2 SNP309 genotype was associated with increased lung cancer risk in women (OR, 1.282; 95% CI, 1.062–1.548) and never smokers (OR, 1.328; 95% CI, 1.119–1.575)." (PMID 23170107, 2012). "The differences in environment and genetic backgrounds may influence the association between the MDM2 SNP309 polymorphism and risk for lung cancer." (PMID 23170107, 2012). "In summary, previous meta-analyses indicated a possible association of MDM2 T309G polymorphism with lung cancer risk among Asians and never-smokers." (PMID 22844496, 2012). "It appears that the results of the subgroup analysis according to females and males was due to smoking and no smoking status as more men smoke than women, and it has been suggested that MDM2 SNP309 increases the risk of lung cancer in never smokers." (PMID 23170107, 2012). "According to the results of this meta-analysis, our main finding was that the MDM2 SNP309 polymorphism was statistically significantly associated with the risk of lung cancer in females but not in males." (PMID 23170107, 2012).
lung carcinoma (continued). "Table IV shows the detailed results of the heterogeneity test, assessment of the most appropriate genetic model, and the association between MDM2 SNP309 T>G polymorphism and lung cancer risk evaluated using odds ratios (ORs) with 95% confidence intervals (CIs)." (PMID 23170107, 2012). "In the present updated meta-analysis, the data confirmed the relationship between MDM2 T309G genetic variation and lung cancer risk among individuals who have no smoking history." (PMID 22844496, 2012). "Thus, eight case-control studies (6,696 lung cancer cases and 7,972 controls) concerning the associated of the MDM2 SNP309 polymorphism and lung cancer risk were included in this meta-analysis." (PMID 23170107, 2012). "The overall data failed to indicate a significant association between MDM2 T309G polymorphism and lung cancer risk (GG vs TT OR = 1.14; 95%CI = 0.95−1.37; dominant model: OR = 1.05; 95%CI = 0.92−1.19; recessive model: OR = 1.12; 95%CI = 0.99−1.27)." (PMID 22844496, 2012). "The results thus demonstrate that the MDM2 SNP309 TT rather than the GG genotype is associated with increased risk of lung cancer in this population, suggesting that other mechanisms independent of increased MDM2 levels can influence cancer susceptibility." (PMID 20219101, 2010). "In summary, we show here that the MDM2 SNP309 TT genotype is associated with a higher risk of lung cancer among never smoking women in the Chinese population." (PMID 20219101, 2010). "In conclusion, our findings suggest that the MDM2 SNP309 TT genotype is a risk factor for lung cancer in never-smoker Chinese females." (PMID 20219101, 2010). "We used 635 Caucasian patients diagnosed with lung cancer before 51 years of age and 1300 healthy gender and age frequency matched population Caucasian controls to investigate the association between the MDM2 SNP309 and the risk of developing early onset lung cancer." (PMID 18433484, 2008). "Targeting EZH2, MDM2, and other identified proteins may inhibit tumor growth, enhance treatment responsiveness, and disrupt critical cancer pathways, offering promising strategies for the development of effective lung cancer therapies." (PMID 40070571, 2025). "Therefore, targeted inhibition of the FOXO3a/DNMT3B/MDM2 axis might be seen as a new therapeutic direction for lung cancer treatment, making the existence of the epigenetic linkage with this pathology evident." (PMID 39165584, 2024). "However, MDM2 also stabilizes SLUG mRNA in lung cancer cell lines." (PMID 34944497, 2021). "Among lung cancers with aberrant MDM2 signaling, anti-MDM2 agents may enhance CSC eradication." (PMID 34680249, 2021). "The meta-analysis showed no associationbetween lung cancer and MDM2 (rs2279744) under any model." (PMID 33959694, 2020).
lung carcinoma (continued). "For the overall data, the results showed that MDM2 T309G might not have a correlation with increased lung cancer risk." (PMID 22844496, 2012). "In conclusion, the current meta-analysis demonstrates that the MDM2 SNP309 GG genotype may increase the risk of lung cancer particularly in Asians, females and never smoking population." (PMID 23170107, 2012). "Compared to the previous meta-analyses, the results of this study confirmed that MDM2 T309G polymorphism might be a risk factor for lung cancer among never-smokers." (PMID 22844496, 2012). "Thus, it is not inconceivable that the mechanisms by which MDM2 modulates lung cancer risk can differ between populations." (PMID 20219101, 2010). "Also no influence in lung cancer risk by the MDM2 SNP309 was observed for the diverse histological subtypes of lung cancer." (PMID 18433484, 2008). "In lung cancer, RLIM interacts with MDM2, promoting the ubiquitination‐mediated degradation of MDM2." (PMID 39534556, 2024). "Mouse double minute 2 (MDM2) can bind to and sequester NDUFS1 to reduce mitochondrial respiration and increase mROS, ultimately leading to apoptosis in lung cancer cells." (PMID 37644092, 2023). "Mechanistically, PPDPF interacted with BABAM2 (an antiapoptotic protein) and blocked its ubiquitination by MDM2, thus stabilizing BABAM2 and promoting the radioresistance of lung cancer cells." (PMID 34975328, 2022). "However, polymorphism MDM2(rs2279744) may not impart susceptibility to lung cancer ineither Asians or Europeans." (PMID 33959694, 2020). "The potential therapeutic targets of bufalin included MDM2, PIK3CA, MAPK14, and MTOR, which can induce cell death through various mechanisms and exert anticancer properties against lung cancer, liver cancer, and other tumors." (PMID 32148531, 2020).
lung carcinoma (continued). "Mittelstrass K., Sauter W., Rosenberger A. Early onset lung cancer,cigarette smoking and the SNP309 of the murine double minute-2(MDM2) gene." (PMID 33959694, 2020). "MDM2 and matrix metalloproteinase 9 (MMP9) expressions are related to the formation and migration of lung cancer; therefore, they can serve as the markers for the treatment and prognosis of the disease." (PMID 31885751, 2019). "In leukemia, HDAC2 silencing induces modulation of gene expression leading to strong transcriptional activation while in lung cancer, HDAC2 has been proposed to exert an effect on survival by sustaining Mdm2-survivin levels." (PMID 26683361, 2016). "In this study, transcriptome profiling and RT-qPCR validation revealed that PGL arrests the cell cycle via downregulation of the expression of RB1, CCNH, MDM2, ACCN4, CCND2, GADD45A, and GADD45B in lung cancer cells." (PMID 27355352, 2016). "The same conclusions were drawn from combinations of MDM2 and MEK inhibitors in the RT4 (bladder cancer), RKO (colorectal cancer), A427 (lung cancer), and C32 (melanoma) cell lines." (PMID 24810962, 2014). "Therefore, overexpression or amplification of MDM2, which has also been reported in leukemia and lung cancers, in cells with compromised MLL histone methyl transferase function could accelerate untimely DNA replication, which is known to induce gene abnormality." (PMID 24163099, 2014). "Notably, NFATc1 expression was significantly and positively correlated with MDM2 levels in multiple cancer types, including CRC, gastric cancer, and lung cancer." (PMID 41203626, 2025). "Biologically, we established that MDM2-mediated TOP2β degradation increases cancer cell survival, since its inhibition by RG7112 decreases the survival of lung cancer cells synergistically with VP-16 treatment, resulting in increased apoptosis and higher sensitivity to VP-16 treatment." (PMID 38263255, 2024). "Radiation upregulated miR-155-5p in lung cancer cells, suggesting that miR-155-5p may improve radiosensitivity, and its radiation targets MAP3K20, GTF2H5, GATA3, and MDM2 were identified." (PMID 37569824, 2023). "In lung cancer, RLIM can interact with MDM2 and degrade MDM2 by ubiquitination." (PMID 36756159, 2023). "Three other drugs (SJ‐172550 for MDM4, nutlin‐3 for MDM2/MDM4, and carfilzomib for PSMA6 and PSMB6) showed improved IC50 values when used as a monotherapy but increased efficacy when used in combination with erlotinib on NCI‐H820 lung cancer cell lines." (PMID 33188726, 2021). "Among them, SMURF1, MDM2, SMURF2, TRIM27, and NEDD4L are involved in lung cancer progression." (PMID 33264103, 2020).
lung carcinoma (continued). "Classification of primary lung cancer patients with respect to genotypes of NRF2 and MDM2 genes." (PMID 24040073, 2013). "No overall association between MDM2 SNP309 and lung cancer risk was observed in recent studies in a European, North American and two Asian populations." (PMID 20219101, 2010). "Studies have shown that in lung cancer, after aberrant splicing, the expression of BCL2L1, MDM2, MDM4, NUMB, and MET may play an important role in tumorigenesis, which may be due to the effects on cell apoptosis, cell proliferation, and intercellular cohesion‐related pathways." (PMID 33047900, 2020). "Thus, the association between MDM2 SNP309 polymorphism and lung cancer outcomes has not been evaluated because of the insufficient information provided by the included studies." (PMID 22844496, 2012). "However, the results were not always consistent, possibly attributable to the fact that the majority of studies featured only a small number of samples or the association between the MDM2 SNP309 polymorphism and lung cancer risk did not achieve statistical significance." (PMID 23170107, 2012).